IL18 (interleukin 18)
Diseases named in the same sentence as IL18 in open-access papers (continued):
Sharing a sentence is not in itself a finding about the gene and the disease.
viral infection (continued). "Through induction of IFN-gamma IL-18 primes mononuclear phagocytes for TNF-alpha-induced IL-6 expression, which might be particularly relevant during the later stages of viral infection." (PMID 35860660, 2022). "Furthermore, MAIT cells express receptors for IL-12, IL-18, IL-15 and type I IFN, and are activated by these cytokines to respond rapidly during viral infection." (PMID 35562666, 2022). "During viral infection, DNA or RNA viruses that serves as PAMPs are recognized by a sensor of TLR or NLR results in the transcription and expression of the NLRP3 inflammasome, pro-IL-1β, and pro-IL-18 via NF-κβ upregulation (signal 1 or priming)." (PMID 34638790, 2021). "Similar to what we observed for AB14 (H5N1), the IL-18 gene transcript was not upregulated in response to viral infection, whereas the gene transcription of the anti-inflammatory cytokine IL-10 dramatically increased from 2 to 7 d.p.i." (PMID 30813415, 2019). "When the expression of caspase-1 was inhibited by caspase-1 siRNA, the infection of CVB3 or EV71 failed to elicit the elevated maturation of both IL-1β and IL-18, indicating that the maturation of both cytokines depends on caspase-1 during viral infection." (PMID 29440739, 2018). "Indeed, MAIT cells are activated by IL-18 in synergy with IL-12, IL-15, and IFN-α/β in virus infections." (PMID 29250077, 2017). "Next, we determined the function of MAIT cells in different viral infections and observed that MAIT cells are equally capable to become activated and produce IFN-γ upon stimulation with IL-12/18 and IFN-α/IL-18 in CHCV, HIV, AHCV/HIV co-infection and healthy individuals." (PMID 27416100, 2016). "Unlike many bacterial infections, viral infections are commonly characterized by elevated plasma levels of the pro-inflammatory cytokine IL-18, together with increased circulating ferritin concentrations." (PMID 27977798, 2016). "IL-18 is known to augment IL-12-induced IFN-γ production by T and NK cells, and absence of IFN-γ in infected mice is known to abolish both NK cell and CTL responses during viral infections." (PMID 22206036, 2011). "Our results revealed elevated levels of both TL1A and IL-18 during PVM- and MCMV-induced acute thymus atrophy, suggesting that they might play a role in triggering acute thymus atrophy during viral infections, similar to what was observed following the in vivo administration of these two cytokines." (PMID 38839915, 2024). "In addition, IL-18 may play a potent role in activating CD8+ T cells, which have activity against viral infection." (PMID 36032110, 2022). "Additionally, flagellin activates IL-22 and IL-18 activation through TLR5/NLRC4, driving IL-18-induced apoptosis of viral infection as well as IL-22-induced proliferation, thereby inhibiting viral infection." (PMID 35216425, 2022). "However, IL18 presence will also further mediates the host’s innate immune response., Nevertheless, the increase of Homeobox 1 expression in IBDV-infected BF remains elusive and yet to be understood in relation to viral infection." (PMID 34147086, 2021). "Interestingly, from titers of 101 to 104 TCID50/0.1 mL, there was a significant increase in IL-18 mRNA levels but this was independent of the virus infection level." (PMID 29245947, 2017). "A likely explanation resides in the origin of circulating IL-18, with monocytes/macrophages being the main source of IL-18 in diseases of bacterial origin, while the largest amount of circulating IL-18 in MAS and viral diseases might originate from damaged endothelium." (PMID 27977798, 2016). "Other than in inducing IFN-γ, IL-18 alone activates the cytotoxic T cells that are also known as CD8+ T cells, which play an important role in viral clearance, suggesting that this cytokine could influence the outcome of viral infection." (PMID 27682100, 2015).
viral infection (continued). "While viruses do not produce MR1-ligands, viral infections efficiently induce MAIT cell activation mediated by a variety of cytokines secreted by host cells such as IL-12, IL-15, IL-18 or type-I IFNs." (PMID 39128630, 2024). "Third, serum IL-18 and sIL-2R are not specific markers for DLBCL and its level are increased in several inflammatory conditions including viral infection and autoimmune disorders." (PMID 31608153, 2019). "Upon cytokine-mediated activation in viral infections, MAIT cells can produce IFN-γ and GzmB, which can be suppressed or even abrogated by anti-IL-18 but not by MR1-blocking." (PMID 29176983, 2017).
Insulin resistance (160 papers, 2008 to 2026). Increased resistance towards insulin, that is, diminished effectiveness of insulin in reducing blood glucose levels. "In PCOS, elevated levels of IL-18 are associated with systemic and visceral obesity as well as insulin resistance." (PMID 41490440, 2026). "In T2D, interleukins like IL-6 and IL-18 contribute to insulin resistance and the inflammatory environment associated with obesity." (PMID 40804870, 2025). "NLRP3 drives the maturation and release of IL-1β and IL-18, cytokines implicated in insulin resistance and metabolic derangement." (PMID 40558557, 2025). "Cross-sectional studies have indicated that IP-10 levels, IL-6, interleukin 18 (IL-18), and adiponectin, are linked to insulin resistance." (PMID 40094974, 2025). "Compared to IL-6 and TNF-α, which also contribute to systemic inflammation in PCOS, IL-18 appears to have a stronger association with insulin resistance." (PMID 40385768, 2025). "Initially, IL-18-deficient (Il18−/−) mice have been described as hyperphagic and obese, exhibiting secondary hepatic insulin resistance." (PMID 41275524, 2025). "IL-18-deficient mice exhibit hyperinsulinemia, consistent with insulin resistance related to hyperglycemia, primarily due to enhanced liver gluconeogenesis and defective STAT3 phosphorylation." (PMID 40243151, 2025). "In contrast, IL‐18 administration is associated with reduced weight gain and IL‐18‐deficiency increases insulin resistance." (PMID 39327931, 2025). "Particularly, IL-18, a pro-inflammatory cytokine, is closely linked to insulin resistance and metabolic syndrome." (PMID 40181376, 2025). "IL-18 has been previously reported to be upregulate in obese, insulin-resistant individuals, with this cytokine being tightly associated with insulin resistance; this relationship was confirmed as part of this study." (PMID 37049621, 2023). "Circulating IL18 level is associated with body weight, insulin resistance, and metabolic syndrome in humans and mice." (PMID 37680891, 2023). "Il-18 is a proinflammatory cytokine that belongs to the IL-1 superfamily and is closely associated with insulin resistance, metabolic syndrome, and is an important predictor of long-term cardiovascular mortality." (PMID 35600955, 2022). "It is possible that IL-6 in combination with other inflammatory markers such as IL-1b, TNF-a, IL-18 and IL-17 links insulin resistance to NMOSD risk." (PMID 33879088, 2021). "Il-18 is a proinflammatory cytokine which belongs to the IL-1 superfamily and is closely associated with insulin resistance, metabolic syndrome, and is an important predictor of long-term cardiovascular mortality." (PMID 33917519, 2021). "The amounts of IL-1β and IL-18 are highly implicated in the development of insulin resistance, type 2 diabetes mellitus (T2DM) and obesity-associated inflammation." (PMID 32650482, 2020). "These animals were fed a high fat diet (HFD), which leads to an increase in pro-inflammatory cytokines, such as IL-1β and IL-18, both of which cause high levels of systemic inflammation and insulin resistance." (PMID 32650482, 2020). "Previous studies have reported that mice deficient in IL-18 developed hyperphagia, obesity, and insulin resistance." (PMID 29514661, 2018). "Given the strong link between ceramides and insulin resistance and mitochondrial function, we further studied the possible association of muscle IL-18 mRNA with ceramides and other sphingolipids." (PMID 29342149, 2018). "This upregulated IL‐18R/IL‐18 gene expression in the adipose tissue was found to be associated with tissue inflammation and insulin resistance." (PMID 28508444, 2017). "IL-18 has been shown to be a marker of metabolic disease, insulin resistance, and CVD risk, and is reduced following exercise and diet." (PMID 27067270, 2016).
Insulin resistance (continued). "Starting at age 16 weeks of age, IL-18-deficient mice start to overeat, become obese, and exhibit lipid abnormalities; there is increased atherosclerosis, insulin resistance, and diabetes mellitus reminiscent of the metabolic syndrome." (PMID 24115947, 2013). "Association of IL18 variation with insulin levels and estimates of insulin resistance were only observed in our adult study, suggesting that the effects of IL-18 are only associated with increasing age." (PMID 20227263, 2011). "In conclusion, the association of genetic variation within IL18 on insulin levels and estimates of insulin resistance were only observed in our older GrOW study, suggesting that the effects of IL-18 appear to be more prominent as we age." (PMID 20227263, 2011). "Exiting evidence also indicated that circulating IL-18 was positively associated with insulin resistance, metabolic syndrome (MetS) and type 2 diabetes, suggesting potential applications of IL-18 as an intervention target or prognostic biomarker." (PMID 21437204, 2011). "In addition, increased plasma levels of IL-18 have been associated with various metabolic parameters, such as hepatic enzymes, lipid profiles, estimates of insulin resistance, and cardiometabolic syndrome in uninfected participants." (PMID 41601646, 2026). "Increased IL‐18 levels in obese individuals have been associated with insulin resistance." (PMID 39327931, 2025). "IL-18 is implicated in chronic inflammation, insulin resistance, and the development of T2D." (PMID 41465472, 2025). "IL-18 is a pro-inflammatory cytokine belonging to the IL-1 family, primarily secreted by macrophages and other immune cells, which is strongly implicated in metabolic disorders, including insulin resistance, obesity, and cardiovascular disease." (PMID 40385768, 2025). "In addition, the expression levels of NLRP6 and IL18 were highly associated between them and also with insulin resistance, strengthening their involvement in glucose metabolism." (PMID 38315242, 2024). "In addition, the variation of IL-18 in the blood is associated with insulin resistance and the level of IL-18 in the bloodstream is associated with the physical exercise of the individual." (PMID 37457235, 2023). "Insulin resistance, metabolic syndrome and T2D are associated with elevated IL-18 levels." (PMID 36301817, 2022). "Additionally, the elevated expressions of the NLRP3 inflammasome, IL-1β, and IL-18 in adipose tissues are directly associated with insulin resistance and severity of diabetes." (PMID 36187801, 2022). "Inflammatory cytokines, e.g., IL-1family members (IL-1α, IL-1β, IL-1Rα, IL-18, IL-33, IL-36, IL-37, and IL-38), are associated with the regulation of atherosclerosis, insulin resistance, and adipose tissue inflammation, all of which are common features of NAFLD." (PMID 31597283, 2019). "Production of VLDL-TG is in part due to be the increased flux of FFA to the liver in combination with insulin resistance associated hyperinsulinemia and this may be a way linking the role of IL-18 in skeletal muscle to dyslipidemia." (PMID 29342149, 2018). "Finally, besides being associated with insulin resistance, IL-18 may also contribute to its pathogenesis." (PMID 37049621, 2023). "It has been demonstrated that activation of NLRP6 promotes IL-18 secretion, which helps maintain intestinal barrier integrity and prevents excessive systemic inflammation that contributes to insulin resistance." (PMID 40433411, 2025). "With regard to metabolic syndrome, elevated IL-18 levels can contribute to insulin resistance by increasing the production of other inflammatory cytokines like TNF-α and IL-6, which interfere with insulin signaling pathways." (PMID 40277935, 2025). "Elevated IL-1β and IL-18 levels are consistently observed in the adipose tissue and serum of individuals with obesity and insulin resistance, and higher NLRP3 expression in visceral adipose tissue correlates with the severity of insulin resistance." (PMID 40943225, 2025).
Insulin resistance (continued). "IL-18 contributes to insulin resistance and β-cell dysfunction and is upregulated in renal tissues during hyperglycemia." (PMID 41480362, 2025). "Among the interesting cytokines and chemokines that decreased substantially, we found the well-known and highly pro-inflammatory cytokines IL-6, TNF, and IL-18 whose roles in adipose tissue-driven inflammation and insulin resistance are well-established." (PMID 40423925, 2025). "Its activation by hyperglycemia, saturated fatty acids, ceramides, and other endogenous danger signals leads to the secretion of IL-1β and IL-18, promoting insulin resistance, endothelial dysfunction, and atherosclerotic progression." (PMID 40648980, 2025). "IL-18 promotes NFκB and MAPK activation and is associated with insulin resistance, atherogenesis, and metabolic syndrome." (PMID 41373925, 2025). "This complex is responsible for releasing proinflammatory cytokines Interleukin-1β (IL-1β) and Interleukin-18 (IL-18), fulfilling a critical function in regulating insulin resistance." (PMID 39995417, 2025). "Nevertheless, our analysis highlights a distinct connection between heightened Metrnl levels and various markers of generalized and visceral obesity, insulin resistance, and the proinflammatory factor IL-18." (PMID 38275393, 2024). "In light of these findings, we can conclude that our study unveiled a parallel clinical connection between elevated Metrnl levels, visceral obesity, insulin resistance, hyperinsulinemia, and the proinflammatory factor IL-18." (PMID 38275393, 2024). "Il18 ablation in mice led to hyperphagia, obesity, insulin resistance, and decreased energy expenditure." (PMID 37680891, 2023). "Despite the quality of dietary lipids failing the predict insulin resistance, it was able to predict IL-18 plasma levels." (PMID 37049621, 2023). "In agreement with this, individuals with a HOMA-IR ≥ 2.5, set as the cut-off for insulin resistance, had higher IL-18 circulating levels compared with study participants with a HOMA-IR < 2.5 (p < 0.001 d = 0.641)." (PMID 37049621, 2023). "As expected, circulating IL-18 positively correlated with insulin resistance assessed by HOMA-IR (p < 0.001)." (PMID 37049621, 2023). "In this sense, serum levels of IL-18 correlate with insulin resistance and metabolic syndrome components." (PMID 37819510, 2023). "In line with the results relative to insulin resistance, the circulating levels of IL-18 were significantly higher in individuals with metabolic syndrome than their metabolically healthy counterparts (p < 0.05; d = 0.441)." (PMID 37049621, 2023). "Interleukin-18, as a potent proinflammatory biomarker, was shown to be related to indices of adiposity and insulin resistance in PCOS19." (PMID 37355686, 2023). "This is, in fact, the first report describing the relationship between dietary lipid intake, IL-18 circulating levels and insulin resistance." (PMID 37049621, 2023). "IL-18 changes have been correlated with changes in insulin resistance, and some studies have reported alterations in IL-18 levels influenced by lifestyle adjustments, such as exercise." (PMID 36005129, 2022). "Circulating IL18 levels correlate with bodyweight, adiposity, insulin resistance, hypertriglyceridemia, and metabolic syndrome in human and mice." (PMID 36482059, 2022). "But in an obese state, Ly6chigh monocytes infiltrate tissues and differentiate into M1 type macrophages, which produce inflammatory cytokines, such as TNF-α, IL-6, IL-1β, and IL-18, and drive insulin resistance." (PMID 36015301, 2022). "Elevated levels of IL-18 were related to several indices of general and visceral adiposity and insulin resistance in PCOS." (PMID 35263047, 2022). "In T2DM, as well as in insulin resistance, there is increased production of IL-6, IL-1β, IL-18, tumor necrosis factor (TNF-a), alpha-1 antichymotrypsin and C-reactive protein." (PMID 35453527, 2022).